CRYBB3 (crystallin beta B3)
Description:
Crystallins are the dominant structural components of the vertebrate eye lens.
Synonyms: CRYB3; CATCN2; CTRCT22
Tractability: Small molecule: it has a high-quality binding pocket.
Gene: Protein-coding gene on chromosome 22 (25,199,858 to 25,207,359, forward strand). Ensembl gene ENSG00000100053.
Subcellular location (Human Protein Atlas): Microtubules; Cytokinetic bridge; Mitotic spindle
Gene Ontology:
Molecular function: protein binding; structural constituent of eye lens
Biological process: lens development in camera-type eye; visual perception
Genetic constraint (gnomAD): Loss-of-function variants: 35 observed, 29.19 expected, observed/expected ratio (o/e) 1.2, 90% interval 0.92 to 1.59. The upper end of that interval is the gene's LOEUF score, 1.59, which puts it in group 6 of 6, group 1 being the genes least tolerant of losing a copy. Missense variants: 291 observed, 306.68 expected, observed/expected ratio (o/e) 0.95, 90% interval 0.86 to 1.05. Synonymous variants: 106 observed, 115.11 expected, observed/expected ratio (o/e) 0.92, 90% interval 0.79 to 1.08.
Homologues: Orthologues: chimpanzee CRYBB3 (98% identical), macaque CRYBB3 (96% identical), dog CRYBB3 (92% identical), mouse Crybb3 (92% identical), pig CRYBB3 (91% identical), rat Crybb3 (91% identical), guinea pig CRYBB3 (89% identical), rabbit CRYBB3 (77% identical), tropical clawed frog crybb3 (69% identical), zebrafish crybb3 (68% identical). Paralogues in human: CRYBB2 (52% identical), CRYBB1 (51% identical), CRYBA1 (41% identical), CRYBA2 (40% identical), CRYBA4 (37% identical), CRYBG2 (33% identical), CRYBG1 (31% identical), CRYBG3 (30% identical), CRYGC (29% identical), CRYGS (29% identical), CRYGA (28% identical), CRYGD (28% identical), and 2 more.
Diseases named in the same sentence as CRYBB3 in open-access papers:
CRYBB3 is named in the same sentence as 11 diseases in open-access papers, as found by Europe PMC text mining. Sharing a sentence is not in itself a finding about the gene and the disease. The quoted sentences say what the papers report.
cataract (4 papers, 2016 to 2024). Partial or complete opacity of the crystalline lens of one or both eyes that decreases visual acuity and eventually results in blindness. "For the lens, which is largely made up of crystallins, we find many crystallin genes (Crybb3, Cryba1, Crybb1, Crygc, Crygs, etc.)in our accelerated set of genes contributing to various forms of cataracts." (PMID 29035697, 2017).
congenital cataracts (4 papers, 2016 to 2024). "Here, we report a common ancestral mutation in CRYBB3 associated with autosomal recessive congenital cataracts identified in four familial cases of Pakistani origin." (PMID 27326458, 2016). "Here, we report a common ancestral mutation in CRYBB3 associated with autosomal recessive congenital cataracts identified in four consanguineous Pakistani families." (PMID 27326458, 2016). "A subset of the 7-days radiation only DEG (Cryaa, Cryba1, Cryba2, Cryba4, Crybb1, Crybb2, Crybb3, Crygs, Bsfp1) were enriched in nuclear and congenital cataracts, however, these genes were not dysregulated at 1 month or 4 months." (PMID 36207342, 2022).
microphthalmia (2 papers, 2021 to 2023). Congenital or developmental anomaly in which the eyeballs are abnormally small. "Mutations or abnormal expression in CRYBB3 would lead to severe developmental disorders of eye development, such as poor vision, cataract, corneal degeneration, or some form of microphthalmia (syndrome with unusual smaller eyes) in Humans." (PMID 37629073, 2023).
nuclear cataract (2 papers, 2010 to 2016). A cataract (disease) that involves the lens nucleus. "We previously reported two familial cases of Pakistani origin with nuclear cataracts harboring the G165R missense mutation in CRYBB3." (PMID 27326458, 2016). "Previously, nuclear cataracts segregating in consanguineous families have been mapped to chromosome 2p12, 19q13.4, and 22q12.3, in the latter of which mutations in CRYBB3 were identified." (PMID 20161816, 2010).
diabetes (1 paper, 2018). "From our RNA sequencing analysis, it emerges that diabetes and the metabolic syndrome induce the expression of crystallin β (i.e. Crybb3, Cryba2, Cryba1) and γ (i.e. Crygc, Crygb, Crygf) in the retina, whereas we did not observe any significant effect on α crystallins." (PMID 30093686, 2018). "However, Crybb3, Cryba2, Crygc, Crygb, Crygf, Cryba1 were only upregulated in obese 42, indicating that their expression was likely affected by diabetes and metabolic diseases." (PMID 30093686, 2018).
lung carcinoma (1 paper, 2022). "We picked the top 5 genes (ZNF24, NR3C2, CST4, ARHGDIG and CRYBB3) to confirm their lung cancer suppressive function." (PMID 36457047, 2022).
CRYBB3 also shares sentences with these, for which no sentence is quoted: Age-related cataract (1 paper); corneal degeneration (1); metabolic disease (1); metabolic syndrome (1); retinal degeneration (1).